KIT (KIT proto-oncogene, receptor tyrosine kinase)
Diseases named in the same sentence as KIT in open-access papers (continued):
Sharing a sentence is not in itself a finding about the gene and the disease.
myocardial infarction (23 papers, 2003 to 2025). Gross necrosis of the myocardium, as a result of interruption of the blood supply to the area, as in coronary thrombosis. "On the other hand, KIT-negative ECs were expanded independently of METRNL-KIT signaling, suggesting that different subsets of ECs proliferate via distinct mechanisms in response to myocardial infarction." (PMID 36544808, 2023). "However, in a myocardial infarction model, Metrnl demonstrated angiogenic effects through KIT-dependent signaling pathways." (PMID 38745648, 2024). "Two patients in whom no KIT mutations were detected (cases 5 and 8) died of myocardial infarcts 9 and 13 months, respectively, after imatinib induction." (PMID 12888812, 2003). "In contrast, VEGFA (0.919; 0.847–0.998; P = 0.044), KIT (0.754; 0.575–0.988; P = 0.041), TNF (0.881; 0.796–0.974; P = 0.014), CTNNB1 (0.920; 0.858–0.986; P = 0.018), and GGT1 (0.887; 0.796–0.989; P = 0.030) were associated with lower risk of myocardial infarction." (PMID 41573742, 2025). "In the recent outcome analysis of the phase 3 clinical PERFECT trial we are investigating intramyocardial transplantation of c-KIT/CD117+/CD133+,/CD34+ bone marrow derived hematopoeitic stem cells (BM-HSC) in post-myocardial infarction (MI) coronary artery bypass graft (CABG) patients." (PMID 32629392, 2020).
neuroblastoma (23 papers, 2012 to 2025). Neuroblastoma (NB) is the most common solid, extracranial childhood tumor. "Additionally, higher KIT expression in neuroblastoma was associated with poor disease outcomes, as has been shown in previous studies." (PMID 35887076, 2022). "To better understand whether KIT can be viewed as a primary target for RTK inhibitors and other drugs, we used lentiviral vectors encoding shRNA against KIT to selectively downregulate KIT expression in two neuroblastoma cell lines expressing KIT at remarkably different levels." (PMID 35887076, 2022). "We also found statistically significant negative correlations for several apoptosis-related pathways, including mitochondrial apoptosis pathway, although the role of KIT in control of neuroblastoma cells apoptosis needs to be further investigated." (PMID 35887076, 2022). "Further studies on KIT functions in neuroblastoma and the impact of specific inhibitors on tumor stemness and metastasis are warranted." (PMID 34716856, 2022). "Neuroblastoma cells that express high levels of KIT can induce tumors ninefold more efficiently than those with low KIT expression." (PMID 25884760, 2015). "It was shown that inhibition of PTPN11 might be an effective strategy to overcome NRAS-dependent resistance in neuroblastoma or KIT-induced myeloproliferative diseases." (PMID 37384296, 2023). "In turn, KIT expression showed a positive correlation with the ERK cell survival signaling pathway and negative with ATM cell G2-M cell cycle arrest pathway, thus suggesting a possible role of KIT in neuroblastoma cell proliferation, survival, and control of G2/M cell cycle checkpoint." (PMID 35887076, 2022). "However, other reports suggest that expression of KIT statistically correlated to a better prognosis in neuroblastoma tumor samples." (PMID 34716856, 2022). "Neuroblastoma, overall, has an average mean KIT expression similar to most other solid tumors, but like kidney, lung, breast, medulloblastoma, ependymoma, and CNS/PNET tumors, it has a substantial percentage (>5%) sample with high KIT expression (higher than mean KIT expression in AML)." (PMID 35887076, 2022). "Like ALK, KIT is an emerging marker for aggressive neuroblastoma that leads to poor prognosis." (PMID 25884760, 2015). "To further characterize possible KIT functions in neuroblastoma we analyzed the correlation of KIT expression and activation levels of signaling pathways, calculated using the Oncobox method for 60 previously published NB tumor RNA expression profiles." (PMID 35887076, 2022). "Once more, the fact that some of such RTKs have previously been described as important players in neuroblastoma tumor biology (e.g., ALK, KIT, MET, and RET) again validates this approach." (PMID 34716856, 2022). "The data also suggest that there are different routes to cell proliferation in neuroblastoma, such as the distinct mechanisms activated by the EGFR group, or KIT." (PMID 25884760, 2015). "Several RTKs, including ALK, KIT, MET, NTRK2, and RET, play a major role in neuroblastoma pathogenesis, and their activation could be responsible for adaptive resistance to trametinib and ganitumab in neuroblastoma." (PMID 39001383, 2024). "Tumor infiltration and signaling pathway for immune modulating cytokine IL-2 had a strong negative correlation with KIT expression, which is in line with our conclusion that KIT expression in neuroblastomas is not driven by immune infiltration." (PMID 35887076, 2022). "Interestingly, KIT clustered with ROR1, which is also expressed early in development and is a marker for cell migration and invasiveness in neuroblastoma and other cancers." (PMID 25884760, 2015).
spindle cell tumors (23 papers, 2005 to 2025). "KIT mutations were predominantly found in spindle-cell tumors (72%), while PDGFRA (both D842V and non-D842V) were primarily observed in purely epithelioid or mixed tumors (96%) (p < 0.001)." (PMID 39199677, 2024). "KIT mutations were predominantly found in spindle-cell tumors, whereas PDGFRA mutations were more common in epithelioid and mixed tumors (p < 0.001)." (PMID 39199677, 2024). "The differential diagnosis should consider other spindle cell tumors, and molecular testing for KIT and PDGFRA mutations is essential for both diagnosis and therapeutic planning." (PMID 39559661, 2024). "Molecular exploration of ALK rearrangements and KIT mutations may be required to diagnose KIT-positive spindle cell tumors." (PMID 24938355, 2014). "A possibility of IMT should be included in the differential diagnosis of KIT-positive spindle cell tumors, especially those in the urinary bladder." (PMID 24938355, 2014). "Histologically, a spindle cell tumor that was immunohistochemically positive for both KIT and ALK was also identified." (PMID 24938355, 2014). "It is difficult to differentiate GISTs from other spindle cell tumors, hence the need for immunohistochemistry, the examination of c-KIT gene amplification and sequencing." (PMID 19500398, 2009). "Immunohistochemically the specific marker for KIT (CD117) is used to distinguish GIST from others spindle-cell tumours of the GI." (PMID 17490483, 2007). "Therefore, IMTs should be included in the differential diagnosis of spindle cell tumors, even those that are KIT-positive." (PMID 24938355, 2014). "Therefore, KIT immunopositivity alone cannot differentially diagnose a GIST among spindle cell tumors." (PMID 24938355, 2014). "According to Hirota and colleagues, most GISTs are identified on immunohistochemistry by the expression of CD117 (KIT), which distinguishes them from other spindle cell tumors." (PMID 40027013, 2025). "Dedifferentiated liposarcoma is a spindle cell tumor which is also negative for KIT and anoctamin 1, but with nuclear positivity for mouse double minute 2 protein (MDM2)." (PMID 34442339, 2021). "It is notable that the hallmarks of tumor necrosis were not seen in the one spindle cell neoplasm lacking KIT expression." (PMID 24507750, 2014). "Synovial sarcoma is a spindle cell tumor negative for KIT, but positive for keratin component." (PMID 34442339, 2021).
colon carcinoma (22 papers, 2012 to 2025). "Recent investigations have shown that more differentiated colon tumor cells release SCF, which affects the proliferation of CSC-like colon tumor cells that express c-KIT." (PMID 37298401, 2023). "In ImPACCT, patients with CMS4 colon cancer are identified with a recently developed 4-gene RT-qPCR test that measures PDGFRA, PDGFRB, PDGFC and KIT expression levels in diagnostic tumour biopsies." (PMID 28424071, 2017). "In ImPACCT we aim to deliver proof-of-concept that PDGFR/KIT inhibition with imatinib reduces the aggressive phenotype of newly diagnosed primary CMS4 colon tumours." (PMID 28424071, 2017). "We have previously shown that Platelet-Derived Growth Factor Receptors (PDGFRs) and KIT are highly expressed in mesenchymal-type colon tumours and that their expression strongly correlates with disease-free survival." (PMID 28424071, 2017). "Research using spheroid cultures obtained from tumor cells from patients with colon cancer grown in serum-free and non-adherent plates—a technique frequently used to study CSCs—have linked c-KIT expression to cancer stemness, and mounting evidence implies a role of c-KIT in colon cancer stemness." (PMID 37298401, 2023). "Moreover, in vitro and in vivo inhibition of PDGFR and KIT tyrosine kinase signalling reduced invasiveness, metastatic potential and stem-like characteristics of mesenchymal-type colon cancer." (PMID 28424071, 2017). "KIT signalling may play a growth-stimulatory role in colon cancer." (PMID 31370857, 2019). "After screening for oncogenes or suppressor genes, KIT, KRAS, BRAF, and JAK2 were significantly higher in colon cancer ECs." (PMID 35755820, 2022). "In colon cancer (CC) cells, wild-type KIT (WT-KIT) was detected only in the PM, regardless of permeabilization." (PMID 37704840, 2023). "Based on these findings we hypothesise that patients with poor-prognosis mesenchymal-type colon cancers could benefit from treatment with imatinib, a tyrosine kinase inhibitor with high selectivity for PDGFR and KIT." (PMID 28424071, 2017). "Accumulating evidence also indicates a role for c-KIT in colon cancer stemness, as supported by studies employing spheroid cultures derived from colon cancer patients’ tumor cells grown in serum-free and non-adherent plates, a technique commonly used to investigate CSCs." (PMID 35490363, 2022).
myeloid leukemia (21 papers, 2009 to 2025). A clonal proliferation of myeloid cells and their precursors in the bone marrow, peripheral blood, and spleen. "In the KIT (D814V)-induced myeloid leukemia mouse model, knockout of ROCK1 increased survival in all mice, while all wild-type control mice died throughout the experiment." (PMID 36561342, 2022). "It has also been reported that knockout of ROCK1 enabled the mice to survive throughout the entire duration of the experiment in a KIT (D814V)-induced myeloid leukemia mouse model." (PMID 36561342, 2022). "We then stained three myeloid leukemia cell lines with an anti-KIT (conjugated with FITC) antibody to determine the expression of KIT on protein level." (PMID 31681584, 2019). "Several studies have demonstrated that CCDC26 controls myeloid leukemia cell growth through regulating KIT expression." (PMID 31619233, 2019). "We suggest that CCDC26 controls growth of myeloid leukemia cells through regulation of KIT expression." (PMID 25928165, 2015). "Work with a c-KIT expressing human myeloid leukemia cell line proved that STI 571 (imatinib mesylate) was able to block c-KIT autophosphorylation." (PMID 22665999, 2012). "A previous study demonstrated that RELA could form a complex with SP1 and bind to the promoter region of KIT in myeloid leukemia cells." (PMID 31363162, 2019). "Interestingly, it has been recently suggested that CCDC26 could control myeloid leukemia cell growth through regulation of KIT expression." (PMID 29464086, 2018). "First, we measured the mRNA expression of two KIT isoforms (GNNK+ and GNNK-) in three myeloid leukemia (Kasumi-1, K562, and HL-60) and three NB (SH-SY5Y, SK-N-BE, and SK-N-AS) cell lines." (PMID 31681584, 2019). "The pathways and genes that significantly changed were classified as follows: cancer pathways (EPAS1, CCND1, FGF13), myeloid leukemia pathways (ZBTB16, KIT, IL13), hematopoietic cell lineage pathways (EPOR, GYPA, CD36) and so on." (PMID 27516205, 2016). "For example, the extent of expression of the myeloid-skewed marker KIT in ETP-ALL was comparable to that in AML, and was significantly higher than those in non-myeloid leukemia such as B-ALL and T-ALL, further validating the correlation between its expression and myeloid lineage bias." (PMID 35646901, 2022). "Likewise, in myeloid leukemias, NSC/LSC express receptors for various regulators of normal stem cells, including the IL-3 receptor (CD123/CD131), SCF receptor KIT (CD117), or G-CSF receptor (CD114)." (PMID 25886184, 2015).
myeloproliferative neoplasm (21 papers, 2009 to 2025). A clonal hematopoietic stem cell disorder, characterized by proliferation in the bone marrow of one or more of the myeloid (i.e., granulocytic, erythroid, megakaryocytic, and mast cell) lineages. "To extend the knowledge on how KIT regulates hematopoiesis and contributes to myeloproliferative disorders, we studied the effects of ectopic KITD816V expression in the adult hematopoietic system." (PMID 28128288, 2017). "Although the dual BCR-ABL/SRC TKI dasatinib inhibits the kinase activity of KIT D816V in vitro and has demonstrated efficacy in other myeloproliferative neoplasms, such as CML, it has displayed minimal activity in patients with SM." (PMID 26002753, 2015). "In addition, A674563 exhibited strong binding to ROCK1 kinase as well, which has been implicated to play roles in the c-KIT, FLT3 and BCR-ABL oncogenes mediated myeloproliferative diseases." (PMID 27074558, 2016). "In another study, downstream of activated KIT D814V receptor, a PI3Kinase/RHOA mediated activation of ROCK1 was shown to induce transformation and myeloproliferative neoplasm in mice." (PMID 26158763, 2015).
myeloid neoplasm (20 papers, 2017 to 2026). Proliferation of myeloid cells originating from a primitive stem cell. "A retrospective study preliminarily presented the distribution of KIT mutation in myeloid neoplasms, including 56% patients with CBF-neg AML and 45% with CBF-AML." (PMID 41557053, 2026). "The associated myeloid neoplasms often share KIT mutations and/or other genetic abnormalities with SM, whereas KIT mutations are not found in lymphoid or plasma cell neoplasms co-occurring with SM." (PMID 36980550, 2023). "Our patient showed an evolution from KIT mutated indolent SM to a myeloid neoplasm with PDGFRA rearrangement; when the eosinophilic component expanded, a regression of the MC counterpart was observed." (PMID 34917498, 2021). "In the 2022 ICC, myeloid neoplasms are the exclusive related hematologic conditions due to their shared KIT mutations and clonal abnormalities with SM, distinguishing them from lymphoid neoplasms that co-occur with SM but lack KIT mutations." (PMID 38067330, 2023). "However, if monocytosis, eosinophilia, splenomegaly, elevated LDH, high KIT D816V variant allele frequency, and/or additional somatic mutations in genes associated with myeloid malignancies are identified, it should prompt careful evaluation to exclude SM-AHN." (PMID 38067330, 2023). "Recently reported data collected from deep targeted sequencing indicated that KIT D816 mutations can be identified in 1–6% of patients with various subtypes of myeloid neoplasms, e.g., MDS, MDS/MPN-u, CMML, polycythemia vera, essential thrombocythemia, or myelofibrosis." (PMID 30635631, 2019). "Myeloid neoplasms are known to have chromosomal translocations that regulate PML-RARA, CBFB-MYH11, and RUNX1-RUNX1T1 myeloid transcription factors and JAK2, FLT3, KIT, and RAS, activating driver mutations in signaling pathways." (PMID 38392574, 2024). "Within our registry, all KIT D816Vmut patients, who had initially been diagnosed as myeloid neoplasms such as CMML, triple-negative MF, and others, in fact fulfilled the WHO-criteria for a diagnosis of SM-AHN." (PMID 30635631, 2019). "Myeloid Malignancy-Related Gene Mutation Screening: A panel of 67 genes associated with the diagnosis, treatment, prognosis, and recurrence of myeloid malignancies (including KIT, SRSF2, TET2, and ASXL2) was analyzed, with no relevant mutations identified." (PMID 40071101, 2025). "The KIT D816V mutation can also be identified in CFU-GM colonies generated from myeloid progenitors and recent data have highlighted the usefulness of these colonies for obtaining a more thorough insight into the clonal architecture of SM and other multimutated myeloid neoplasms." (PMID 30911112, 2019). "Interestingly, genes commonly mutated in AML and other myeloid neoplasms, such as FLT3, NPM1, KIT, RUNX1, and DNMT3A, were absent in our cohort." (PMID 40526100, 2025).